INS (insulin)
Diseases named in the same sentence as INS in open-access papers (continued):
Sharing a sentence is not in itself a finding about the gene and the disease.
diabetes (continued). "Interest in herbal therapies is increasing with the passage of time primarily due to the side effects of current therapeutic agents (oral hypoglycemic agents and insulin) used in diabetes mellitus." (PMID 33178838, 2020). "Diabetes; Insulin; Epidemiology; Public health; Quality of life; Disability; Endocrinology; Metabolism; Metabolic disorder." (PMID 32715137, 2020). "In conclusion, experimental studies have supplied evidence that glucose contributes to increased atherosclerosis in diabetes independently of changes in lipids or insulin." (PMID 33195459, 2020). "Previous efforts toward the use of inhaled insulin formulations for the treatment of diabetes mellitus gave insights on the possible direct effects of insulin on the respiratory airways." (PMID 33330745, 2020). "In vivo studies have demonstrated that β-secretase (BACE-1) regulates the amount of IR and insulin signalling in the liver making inhibitors of this enzyme, to enhance insulin signalling during diabetes." (PMID 32156083, 2020). "In individuals with diabetes, it has been proved to be able to improve insulin sensitivity, lung, immune and cardiovascular function, and it is associated with lower risk of cardiovascular diseases and overall mortality." (PMID 33467285, 2020). "This miRNA is involved in the pathogenesis of diabetes mellitus by influencing the beta-cells proliferation and the insulin secretion, and a role for miR-29a over-expression in insulin resistance has been also described." (PMID 33072549, 2020). "The multitude of effects attributable to BSE, including both promotion of insulin secretion from the pancreas as well as acting as an insulin mimetic itself, likely contributes to its potency in remediating the complications of diabetes." (PMID 33233708, 2020). "Other studies have shown a higher prevalence of depression in subjects with longer duration of diabetes (≥ 5 years), poorer glycemic control (HbA1c > 7%), and patients using insulin." (PMID 32187271, 2020). "For 6 patients (22%), the diabetes therapy regimen changed within 1 year after their cancer diagnosis, with 2 starting insulin after cancer diagnosis." (PMID 33552546, 2020). "The discovery and success of insulin in treating diabetes was so overwhelming that insulin became the key molecule in glucose homeostasis and the role of brain and other mechanisms were practically forgotten." (PMID 33365205, 2020). "Hsa-let-7a-5p is down-regulated in individuals with diabetes, whereas pancreas-specific overexpression of let-7 in mice resulted in impaired glucose tolerance and reduced pancreatic insulin secretion." (PMID 32466456, 2020). "Leveraging the approval of real-time continuous glucose monitors and sophisticated algorithms that partially automate insulin infusion pumps has improved glycemic control, decreasing the burden of diabetes management." (PMID 33217903, 2020). "While hyperglycemia defines diabetes, varying only in severity, insulin resistance coupled with defective insulin secretion is typically found in type 2 diabetes whereas type 1 diabetes is caused by severe insulin deficiency." (PMID 33134327, 2020). "Insulin-producing beta cells sourced from pluripotent stem cells hold great potential as a virtually unlimited cell source to treat diabetes." (PMID 33117786, 2020). "The current standard treatment for diabetes is exogenous insulin, administered either manually or with a controlled pump device." (PMID 33282827, 2020). "Our findings provide a novel approach for the generation of a large amount of autologous insulin-producing cells from patients themselves to potentially treat diabetes in clinics after optimizing ex vivo culture conditions." (PMID 32485922, 2020). "The ability to accurately measure BG on a drop of blood obtained by lancing a fingertip is arguably the most important advance in diabetes management since the discovery of insulin." (PMID 32256447, 2020).
diabetes (continued). "This secreted protein travels with insulin through the bloodstream and gets deposited in the brains of the people having type 2 diabetes mellitus which was similar to patients with Alzheimer." (PMID 32864980, 2020). "Generation of iPSC-derived insulin/glucose-responsive cells in vitro offers great opportunities for both in vitro disease modeling and treatment of diabetes in humans." (PMID 33198288, 2020). "In contrast, in these type 2 diabetic patients, insulin retains its ability to enhance lipogenesis in the liver, creating a negative feedback that sustains the metabolic alterations present in diabetes mellitus." (PMID 33679386, 2020). "We measured the acute effect of insulin administration on cardiac function among patients with diabetes, intending to probe its potential effect on diastolic performance." (PMID 32308680, 2020). "The release of insulin is controlled by the concentrations of glucose, hence, the biocatalytic insulin-loaded hydrogel provides an interesting sense-and-treat carrier for controlling diabetes." (PMID 34122910, 2020). "An acute infusion of reconstituted HDs in thirteen patients with type 2 diabetes mellitus reduced plasma glucose by increasing plasma insulin levels and activating AMP-activated protein kinase in skeletal muscle." (PMID 32264946, 2020). "Early, prediabetic stages of type 2 diabetes mellitus (T2DM) are normally characterized by compensatory hypersecretion of insulin." (PMID 33193079, 2020). "For example, an EHR database containing only disease classifications will represent diabetes but will fail to represent insulin; hence, insulin cannot be predicted." (PMID 32706678, 2020). "Epidemiological studies have linked serum concentrations of dioxin/dioxin-like chemicals with both increased diabetes incidence and decreased insulin secretion in humans." (PMID 31996693, 2020). "Bariatric surgery has been proven to resolve or improve pre-existing type 2 diabetes mellitus during 3- to 5-year follow-up periods and preoperative fasting insulin levels are shown to drop by 45% and 50% in the first 3 months after SG and RYGB, respectively." (PMID 32847052, 2020). "Improvement of the mean glucose levels, along with attenuation of glucose variability, is clinically very important for patients with diabetes who use insulin." (PMID 32352017, 2020). "Insulin treatment is widely used in diabetes therapy, with all T1D patients, and in T2D more than one-third of T2D patients using insulin." (PMID 32382021, 2020). "Daily insulin dose per kg bodyweight (IU/kg/d) in this cohort of individuals with WRS was 0.7 (0.5–0.9) IU at diabetes onset and 0.7 (0.5–1) IU at follow-up in patients aged 2 (1.8–12) years." (PMID 32321554, 2020). "Diabetes mellitus is a metabolic disease when blood glucose levels rise from the normal range due to hormone insulin-related disorders, such as obesity." (PMID 32349282, 2020). "Diabetes mellitus is a multifactorial disease that occurs following the dysfunction or death of insulin-producing β cells in the pancreas." (PMID 32736653, 2020). "Type 2 diabetes (T2D) is the most common form of diabetes, and is characterized by chronic hyperglycemia, peripheral insulin resistance, and insufficient insulin production by pancreatic beta cells." (PMID 31996693, 2020). "This indicates that impairment of central insulin signaling is indeed an important factor for diabetes-induced brain injury." (PMID 32265637, 2020). "Pluripotent stem cell (PSC)-derived insulin-producing cells are a promising cell source for diabetes cellular therapy." (PMID 31988329, 2020). "The present study found that the strongest predictors of ED attendances for both hypo and hyperglycaemia in an unselected population of adults with diabetes were insulin treatment and a prior acute glycaemic event of the same type leading to ED attendance." (PMID 32429960, 2020).
diabetes (continued). "People with type 1 diabetes mellitus (T1DM) need to self-administer insulin to maintain blood glucose (BG) levels in a normal range, which is usually a very challenging task." (PMID 35415447, 2020). "Type 2 diabetes mellitus (T2DM) is a metabolic disorder characterized by an increase in blood glucose due to impaired insulin secretion and its action." (PMID 33261004, 2020). "Oral insulin replacement therapy remains a very appealing alternative to subcutaneous injections for patients with diabetes mellitus." (PMID 32349416, 2020). "For those patients who had authorision, our hospital arranged for a few free anti-diabetes medications (insulin, glibenclamide and glimepiride) to be provided by the hospital diabetes center." (PMID 32695232, 2020). "COVID-19 leads to deterioration of glucose control in patients with diabetes mellitus, likely through direct virus-mediated β-cell injury, cytokine-induced insulin resistance and hypokalemia-related inhibition of insulin secretion." (PMID 33297431, 2020). "The Partial Clinical Remission of diabetes mellitus depends essentially on the endogenous insulin production by residual β cells, and its length depends on the progressive destruction of these pancreatic β cells by the individual's immune system." (PMID 32215008, 2020). "Patients often do not have access to refrigeration, and they are instructed to follow East African Diabetes Study Group Guidelines which recommend insulin storage in a clean container in a cupboard at room temperature." (PMID 32704558, 2020). "Diabetes is a serious chronic disease that occurs in two cases: the pancreas is not able to produce enough insulin or the body cannot effectively use the insulin it produces." (PMID 32560509, 2020). "Diabetes is actually a collection of metabolic illnesses featured with hyperglycaemia arising from the dysfunction in insulin release and activity." (PMID 33145961, 2020). "Prognostic values of VAT and VAT-related indices for insulin sensitivity, HbA1c levels and prediabetes/diabetes were analyzed for males and females." (PMID 32664590, 2020). "GW501516 treatment also markedly improves diabetes by decreasing blood glucose and insulin levels in ob/ob mice." (PMID 32708786, 2020). "Diabetes mellitus (DM) is a chronic disease with dysfunction in insulin secretion that gradually affects critical organs and tissues, including the heart, nerves, blood vessels, and eyes, and increases the risk of their infection." (PMID 32190696, 2020). "Dysfunction of the insulin-secreting β cells, arising from autoimmune destruction or insulin-resistance, results in the development of diabetes mellitus." (PMID 32429597, 2020). "Diabetes mellitus is a metabolic disorder characterized by impaired insulin secretion or the inability of tissues to respond to insulin." (PMID 32259003, 2020). "Alterations in INS metabolism seems to play a role in diseases involving insulin resistance such as diabetes and polycystic ovary syndrome." (PMID 33153126, 2020). "The average age, duration of diabetes and number of years on insulin were 46, 12.21 and 7 years respectively." (PMID 33193981, 2020). "Over time, these states can chronically impair insulin production and/or sensitivity and lead to diabetes." (PMID 33085688, 2020). "In turn, the prevalence of diabetes mellitus as primary renal disease, the use of insulin therapy, the cumulative prednisolone dose, and the time between transplantation and baseline measurements were lower for these subjects." (PMID 31973007, 2020). "Type 2 diabetes mellitus (T2DM) is a chronic health condition that occurs when insulin secretion is impaired and manifests through features associated with insulin resistance." (PMID 32824773, 2020). "We excluded those clinically judged to have exocrine pancreatic disease, monogenic diabetes or insulin-dependence (history of ketoacidosis, unresponsiveness to oral hypoglycaemic agents, on continuous insulin treatment since diagnosis)." (PMID 32528078, 2020).
diabetes (continued). "Type 1 diabetes mellitus (T1D) is described as the partial or complete destruction of insulin-producing beta cells from Langerhans islets in the pancreas, and this causes hyperglycemia." (PMID 33312173, 2020). "Furthermore, GLP-1 may contribute to memory loss as well as improved systemic body function in diabetes by enhancing glucose tolerance and insulin resistance, suggesting that impaired glucose metabolism and poor insulin sensitivity aggravates memory loss and neuroinflammation." (PMID 33328965, 2020). "In terms of treatment cohort, the mean duration of diabetes was shortest in the Gemi Mono group (1.96 years) and longest in the Gemi + INS ± Others group (12.42 years)." (PMID 33149182, 2020). "Such hurdles render insulin poor oral bioavailability, despite the oral route is the most favourable mode of diabetes management." (PMID 33066443, 2020). "Type 2 diabetes mellitus (T2DM) is a syndrome induced by insufficient insulin secretion or impaired insulin secretion, which constitutes the majority of cases; T2DM has become a serious threat to public health and is a growing burden on global economies." (PMID 31939557, 2020). "Diabetes appears to be an important risk factor for developing AD with several studies linking diabetes and impaired insulin signaling in the brain to AD pathogenesis." (PMID 33192310, 2020). "Nevertheless, in 5 patients within this group, the measurement of autoantibodies was performed years after diabetes diagnosis (from 3 to 18 years), although these patients were always under insulin therapy." (PMID 33292447, 2020). "In this article, we outlined the role and possible regulatory mechanisms of insulin, which plays an important role in the course of diabetes, in depression and depression‐like behaviour." (PMID 32281722, 2020). "49.24% of subjects were controlled their diabetes by diet, 6.99% by drug and %6.99 by insulin injections." (PMID 32070359, 2020). "Our study showed that diabetes education courses on the mobile app-based LCCP platform were helpful for improving glycemic control in patients with diabetes treated with insulin." (PMID 32141838, 2020). "A systemaic review conduced by Clarke and colleagues demonstrated that insulin sensitivity was improved following intake of low dietary AGEs in healthy individuals and patients with type 2 diabetes mellitus." (PMID 33335235, 2020). "Metformin is an oral biguanide commonly used in treatment of type 2 diabetes mellitus as a glucose-lowering agent which decreases hepatic gluconeogenesis and improves insulin sensitivity by increasing peripheral glucose uptake and use." (PMID 32977434, 2020). "Of interest is the observation in this study that children with DS and diabetes used less insulin but showed better glycaemic control." (PMID 32839884, 2020). "There is also evidence for aetiological overlap between schizophrenia and diabetes beyond what is attributable to metabolic effects of antipsychotic treatment, which supports our identification of an insulin related pathway as a candidate PES37–39." (PMID 31964963, 2020). "Duration of diabetes, baseline HbA1c and insulin treatment were significantly negatively correlated with the “time-within-remission range”." (PMID 32283783, 2020). "Diabetes mellitus is a metabolic disease characterized by defective insulin secretion and action, which results in hyperglycemia and leads to systemic disorders." (PMID 33255983, 2020). "Diabetic retinopathy in adulthood affects three quarters of people diagnosed with diabetes, a chronic condition that alters the way the body processes glucose and/or produces insulin, the hormone that regulates blood sugar levels." (PMID 33316971, 2020). "The reason for a higher occurrence of urolithiasis in diabetes mellitus has been explained as insulin resistance and lower urine pH through impaired kidney ammonia genesis, promoting uric acid stone formation." (PMID 33005194, 2020).
diabetes (continued). "After only 4.5 months, intensification of diabetes therapy with a third antidiabetic agent or switch to twice daily mixed insulin or prandial insulin was necessary." (PMID 32316649, 2020). "Typically, renal disease occurs in childhood and diabetes mellitus arises in adolescence or early adulthood, with most affected individuals progressively requiring insulin." (PMID 33292863, 2020). "A higher reporting rate of hyperglycemia in female insulin users is in line with previous studies which have indicated that women with diabetes have poorer glycemic control." (PMID 33067519, 2020). "The total daily insulin dose of individuals with WRS registered in DPV was 3.5 (3–4.3) IU at diabetes onset (n = 4) and 9.6 (6.8–12.6) IU at follow-up (n = 10)." (PMID 32321554, 2020). "Guidelines authored by prominent diabetes societies encourage the use of insulin as the preferred treatment during the global pandemic." (PMID 32392473, 2020). "Diabetes is a chronic condition during which the human body loses its ability to produce or properly use insulin." (PMID 33027944, 2020). "Since then, the availability of insulin has shifted the focus of diabetes treatment from trying to keep patients alive to saving and improving the life of millions." (PMID 32894308, 2020). "As such, to understand how lipids regulate hepatic insulin action is still a fundamental matter for the understanding of the pathogenesis of diabetes." (PMID 32917816, 2020). "The primary objective of this study was to evaluate the effectiveness of insulin glargine 300 U/mL (Gla-300) in participants with T2DM previously treated with NPH insulin in Polish diabetes centres." (PMID 32337298, 2020). "Diabetes mellitus (DM) is a metabolic disorder of multiple causes characterized by chronic hyperglycemia with disturbances of carbohydrate, fat and protein metabolism resulting from defects in insulin secretion, insulin action, or both." (PMID 32872226, 2020). "MicroRNAs (miRNAs) play a key role in mediating the action of insulin on cell growth and the development of diabetes." (PMID 32938376, 2020). "Patients with diabetes receiving insulin also tended to have higher left ventricular ejection fractions than the comparison groups." (PMID 33118731, 2020). "Although the CRR during insulin-induced hypoglycemia in the context of diabetes has been long appreciated, it is not fully understood and also likely includes other hormones besides those originally described by Cryer." (PMID 33042003, 2020). "Diabetic ketoacidosis, on the other hand, is a life-threatening complication of diabetes mainly due to the massive breakdown of lipids in adipose tissue induced by insulin deficit." (PMID 33379163, 2020). "Insulin degludec is an ultra-long-acting insulin analogue that is increasingly being used in diabetes due to its favourable efficacy and safety profile." (PMID 33006670, 2020). "Growing evidence strongly supports the role of the mitochondria-ER connection in the insulin resistance of peripheral tissues, pancreatic β cell dysfunction, and the consequent development of type 2 diabetes mellitus (T2DM)." (PMID 33195204, 2020). "Type 2 diabetes mellitus (T2DM) is a chronic disease that occurs when the body becomes resistant to insulin and/or cannot make enough insulin in the pancreas." (PMID 31963383, 2020). "A new evidence‐informed electronic basal bolus insulin therapy protocol to improve diabetes care and practice." (PMID 32802349, 2020). "In the field of diabetes education, AI technologies have been extensively utilized in diabetes prediction, dietary and exercise guidance, insulin injection guidance, monitoring of complications, and self-management." (PMID 32548087, 2020). "In the present study, 17 patients were treated with insulin (10 with diabetes mellitus type 1 and with proteinuria, 1 with diabetes mellitus type 2 and proteinuria, and 6 with diabetes mellitus type 2 and without proteinuria)." (PMID 31936498, 2020).